APLN (apelin)
Diseases named in the same sentence as APLN in open-access papers (continued):
Sharing a sentence is not in itself a finding about the gene and the disease.
periodontitis (continued). "Apelin is an adipokine that has been little studied in relation to periodontitis to date." (PMID 39189510, 2024). "A better understanding of the apelin-APJ system could pave the way for new diagnostic and therapeutic strategies in the treatment of periodontitis." (PMID 39189510, 2024). "Our in vitro experiments, therefore, suggest that apelin may play a modulating role in the pathogenesis of periodontitis." (PMID 39409058, 2024). "Further studies are needed to clarify whether apelin levels in gingiva, sulcus fluid, saliva, and serum are increased or decreased in gingivitis and periodontitis, and whether apelin exerts pro- or anti-inflammatory effects." (PMID 36902162, 2023). "Another study could show that the salivary apelin levels of diabetic patients with periodontitis were increased as compared to healthy individuals." (PMID 36902162, 2023). "In the present study, apelin and APJ were also shown to be produced in periodontal cells and regulated by periodontal pathogenic bacteria, suggesting that apelin and APJ may play an important role in the pathogenesis of periodontitis." (PMID 36902162, 2023). "Furthermore, apelin concentrations were highest in patients suffering from both periodontitis and T2DM, suggesting that apelin may play a role in periodontitis and glucose regulation." (PMID 39409058, 2024). "However, our experiments also showed that this possibly tissue-protective downregulation of apelin and its receptor was no longer observed after 48 h, which may suggest that in persistent periodontal infection, the apelin-APJ system may be of critical importance in the pathogenesis of periodontitis." (PMID 36902162, 2023). "In one study, the serum levels of apelin in periodontally and systemically healthy individuals and in periodontitis patients with and without T2DM were analyzed." (PMID 39409058, 2024). "Recently, Hirani et al30 investigated the serum levels of apelin in periodontally and systemically healthy individuals and in periodontitis patients with and without T2DM." (PMID 39189510, 2024). "We identified the CHEMERIN, HGF, IFN-I, IL16, LIFR, and APELIN pathways as not being active during homeostasis but rather, to be active in periodontitis." (PMID 36193890, 2022). "In addition, our study revealed that PDL cells express apelin and APJ and that these expressions are inhibited by F. nucleatum, suggesting a possible role for this adipokine and its receptor in the pathogenesis of periodontitis." (PMID 36902162, 2023).
subarachnoid hemorrhage (5 papers, 2019 to 2023). A serious neurological disorder characterized by intracranial hemorrhage into the subarachnoid space. "Apelin-13 can ameliorate neurological function after subarachnoid hemorrhage due to the inhibition of ATF6, which reduced ER stress-induced apoptosis and blood–brain barrier disruption." (PMID 36769462, 2023). "Additionally, the apelin/APJ axis has been shown to inhibit inflammasome formation by activating AMPK in various experimental conditions, including subarachnoid hemorrhage and respiratory disease." (PMID 37540330, 2023).
systemic lupus erythematosus (5 papers, 2020 to 2024). An autoimmune multi-organ disease typically associated with vasculopathy and autoantibody production. "Notably, these prognosis-related DEGs were associated with inositol phosphate metabolism, axon regeneration, inflammatory mediator regulation of TRP channels, systemic lupus erythematosus, apelin signaling pathway, and other cancer-related pathways are closely related." (PMID 36983731, 2023).
Abdominal obesity (4 papers, 2021 to 2023). Excessive fat around the stomach and abdomen. "While mice with apelin deficiency increase serum free fatty acid levels, serum FFA and glycerol levels, abdominal obesity, and body fat." (PMID 36093083, 2022). "Apelin also has been reported to reduce levels of WAT, serum triglycerides, FFA and glycerol release, abdominal obesity, fat weight, and fat production in obese rats." (PMID 36093083, 2022). "We hypothesized that apelin to NT-proBNP ratio may be more predictable that these biomarkers alone, especially in T2DM with comorbidities including abdominal obesity." (PMID 35050233, 2022). "Circulating levels of apelin were found to be significantly reduced in patients with HFrEF when compared with those who had HFpEF or had no HF whatsoever, although patients with either abdominal obesity or T2DM have demonstrated elevated levels of the peptide." (PMID 35050233, 2022).
acute coronary syndrome (4 papers, 2017 to 2025). Signs and symptoms related to acute ischemia of the myocardium secondary to coronary artery disease. "A decrease in apelin concentrations was independently associated with CAD severity and acute coronary syndrome incidence." (PMID 40299338, 2025). "Our previous work revealed that plasma apelin concentration was reduced following acute coronary syndrome (ACS) and remained low to 6 months." (PMID 35783816, 2022).
acute respiratory distress syndrome (4 papers, 2020 to 2024). Progressive and life-threatening pulmonary distress in the absence of an underlying pulmonary condition, usually following major trauma or surgery. "Notably, individuals with acute respiratory distress syndrome (ARDS) display a substantial increase in Apelin levels, observed in both lung tissue and plasma." (PMID 38565984, 2024). "Apelin also improves pulmonary hypertension and is a protective factor against acute respiratory distress syndrome (ARDS)." (PMID 36352477, 2022). "Also, the apelin decreases mitochondrial apoptosis, mitochondrial ROS-triggered oxidative damage, and NF-κB activation to inhibit acute lung injury (ALI) and acute respiratory distress syndrome (ARDS)." (PMID 34803519, 2021).
amyotrophic lateral sclerosis (4 papers, 2011 to 2023). Amyotrophic lateral sclerosis (ALS) is a neurodegenerative disease characterized by progressive muscular paralysis reflecting degeneration of motor neurons in the primary motor cortex, corticospinal tracts, brainstem and spinal cord. "IPA toxicity analysis of SOD1 identified superoxide radicals’ degradation as the leading signaling pathway followed by apelin adipocyte signaling, amyotrophic lateral sclerosis signaling, NRF2-mediated oxidative stress response, and sirtuin signaling pathways." (PMID 36672132, 2023).
colitis (4 papers, 2018 to 2022). Inflammation of the colon. "The administration of apelin can enhance lymphatic function of intestinal tissues to ameliorate the progress of colitis in IL-10 deficient mice." (PMID 33334069, 2020). "Apelin is also implicated in colitis and repair of colonic epithelium." (PMID 31492821, 2019). "Investigations conducted on colonic tissue in mice and humans diagnosed with colitis/IBD revealed an increased concentration of apelin." (PMID 36235636, 2022). "In sodium dextran sulfate (DSS)-induced rat and mouse models of colitis, colonic apelin mRNA increased during inflammation as well as the tissue repair stage following the DSS treatment." (PMID 31492821, 2019). "Early on, apelin has been shown to be elevated in the colonic tissue of mice suffering from colitis as well as in humans with IBD." (PMID 30369924, 2018). "The study concludes that increased apelin in early and repair phases of colitis may facilitate recovery of colonic tissue and that exogenous administration of the peptide may be beneficial in human bowel disease." (PMID 31492821, 2019). "In addition, the administration of apelin to Il10−/− mice with established colitis resulted not only in an amelioration of disease by lowering the production of pro-inflammatory cytokines such as TNFα, IL-6, and IL-1β but furthermore enhanced intestinal lymphatic function." (PMID 30369924, 2018).
coronary artery stenosis (4 papers, 2012 to 2022). "So our result suggested that apelin was associated with the extent of coronary stenosis." (PMID 23554778, 2012). "This study indicated the possible correlation of plasma apelin levels with the severity of coronary artery stenosis and early EPCs in humans, and plasma VEGF with early EPCs." (PMID 23554778, 2012). "In patients with stable angina, plasma apelin was found to be negatively correlated with the coronary artery stenosis severity independent of other cardiovascular risk factors." (PMID 32099583, 2020). "The measurement of plasma apelin levels may be useful for predicting the severity of coronary artery stenosis." (PMID 23554778, 2012). "The mechanisms for the asosication of reduced apelin levels with the severity of coronary artery stenosis have not been clarified." (PMID 23554778, 2012).
endometrial cancer (4 papers, 2021 to 2023). Primary or metastatic malignant neoplasm involving the endometrium (mucous membrane that lines the endometrial cavity). "At the same time, we found that these species with high abundance in the EC endometrium were closely related to activating the Apelin signaling pathway, which had been confirmed to be related to the increased risk of endometrial cancer." (PMID 34631710, 2021). "High apelin levels were found to be associated with an increased risk of endometrial cancer." (PMID 33912466, 2021). "Moreover, apelin may be an independent risk indicator for endometrial cancer development in obese women." (PMID 37190027, 2023). "Several studies suggested that serum levels of a certain adipokine, apelin, were increased in endometrial cancer patients with high BMIs compared to those with normal BMIs, and apelin was upregulated in tumor tissues of HGSOC patients with high BMIs." (PMID 34680399, 2021). "The authors also showed significantly higher levels of apelin in obese women with endometrial cancer (243.5 ± 49.2 pg/mL vs. 200.5 ± 52.7 pg/mL), which may indicate the involvement of apelin in the pathomechanism of endometrial cancer development." (PMID 37190027, 2023).
human papillomavirus infection (4 papers, 2020 to 2025). "The results of the KEGG pathways suggested that the noncancer driver genes were associated with human papillomavirus infection, circadian entrainment, apelin signaling pathway, oxytocin signaling pathway, and calcium signaling pathway." (PMID 32017470, 2020).
Infertility (4 papers, 2019 to 2024). "We hypothesize that during early embryonic development, failures in apelin/APJ signaling in GCs of Turner syndrome patients lead to abnormalities in ovarian development, ultimately resulting in early oocyte loss and infertility." (PMID 39543104, 2024). "We, therefore, propose that targeting the APLN/APJ pathway represents a promising approach to assist male diabetic patients to improve their fertility, providing a theoretical basis of clinical application for treating diabetic-associated infertility." (PMID 36443325, 2022). "Apelin and its receptor are expressed in the HPG axis, and apelin has been reported to induce infertility via suppressing reproductive hormones including LH, FSH, and testosterone." (PMID 34257810, 2021). "In conclusion, we showed in a cohort of women affected by infertility that chemerin and omentin expression in FF and GCs is electively increased in the PCOS group, while ECHO women are characterized by high levels of adiponectin, apelin, and APJ, as well as lower plasma AMH and LH levels." (PMID 31382403, 2019).
injury (4 papers, 2018 to 2024). Damage inflicted on the body as the direct or indirect result of an external force, with or without disruption of structural continuity. "In this study, we investigated whether the ERK-Nrf2-HO-1 pathway, which is related to oxidative stress, plays a role in the Apelin-13 anti-AD cell model of nerve injury." (PMID 38790466, 2024). "Collectively, Fc-apelin fusion protein exerts protective effects against LPS-induced liver damage and may serve as a potential therapeutic for endotoxin-induced liver injury." (PMID 30061611, 2018).
kidney failure (4 papers, 2014 to 2023). An acute or chronic condition that is characterized by the inability of the kidneys to adequately filter the blood. "Apelin-13 level was significantly elevated in patients with kidney failure (without vs. with kidney injury: 1439 (648–3250) vs. 2967 (1757–3836), p = 0.005)." (PMID 37510916, 2023).
lymph node metastasis (4 papers, 2016 to 2024). "BCa patients with elevated apelin levels tend to have worse prognoses and apelin expression is associated with lymph node metastasis, tumor size, stage, and histological type." (PMID 39040042, 2024). "Increased levels of apelin were also observed in patients with lymph node metastasis (p = 0.003), as well as distant metastasis (p = 0.002)." (PMID 31547096, 2019). "When the serum Apelin is studied, we only found that GC patients with lymph node metastasis had a higher serum Aplein level compared to those without (P = 0.043)." (PMID 27733135, 2016).
Myocardial fibrosis (4 papers, 2019 to 2023). "Previous studies have found that apelin could inhibit the development of myocardial fibrosis." (PMID 33329030, 2020). "The Masson’s stain evaluated the myocardial fibrosis level, and CVF value was significantly lessened in the Ad-Apelin group in contrast to Ad-GFP group." (PMID 33342766, 2020).
neuropathy (4 papers, 2020 to 2025). A disorder affecting the nervous system that manifests with pain, tingling, numbness, and/or muscle weakness. "The APLN/APLNR pathway may also serve as a promising therapeutic target for the treatment of psychosis and neuropathy." (PMID 32849850, 2020). "Elucidation of the underlying mechanism(s) and the roles of endogenous apelin/APJ system using gene knockout or shRNA-mediated knockdown technology are needed to confirm whether the apelin/APJ system is a viable target for the treatment of human psychosis and neuropathy." (PMID 32231577, 2020).
oral cancer (4 papers, 2018 to 2024). "Under hypoxic conditions, apelin expression increases, and the addition of exogenous apelin has been found to enhance the proliferation and migration of the oral cancer cell line HSC-3 by promoting the phosphorylation of ERK1/2." (PMID 39684225, 2024). "Under hypoxic conditions, apelin expression was upregulated and exogenous apelin could stimulated the proliferation and migration of oral cancer cell line HSC-3 through phosphorylation of ERK1/2." (PMID 33912466, 2021). "Additionally, apelin stimulated proliferation and migration of oral cancer cells." (PMID 29875677, 2018). "Also, in the human oral cancer cell line, HSC-3, apelin promotes cell proliferation through phosphorylation of ERK1/2." (PMID 36776217, 2023).
proliferative diabetic retinopathy (4 papers, 2011 to 2023). Advanced retinopathy due to diabetes mellitus characterized by the formation of new vessels in the retina. "Nevertheless, the mRNA levels of APJ, apelin, and VEGF are all upregulated in the vascular tissue membrane in proliferative diabetic retinopathy, and apelin/APJ was demonstrated to be involved in retinal neoangiogenesis by promoting the expression of VEGF." (PMID 36902176, 2023). "Previously, we proved that vitreous concentrations of apelin were significantly higher in the proliferative diabetic retinopathy (PDR) group." (PMID 26491547, 2015). "Besides, recent studies suggest that apelin may be involved in retinal neovascularization during the development of proliferative diabetic retinopathy." (PMID 21552499, 2011).
steatosis (4 papers, 2011 to 2025). Increased lipid within the cytoplasm of cells. "In the present study, in skeletal muscle of HFD+EPA mice, the apelin/APJ system was up-regulated, a better use of lipids was shown matching with the decreased steatosis and decreased fat mass." (PMID 24244380, 2013).
toxoplasmosis (4 papers, 2021 to 2025). A parasitic disease contracted by the ingestion or fetal transmission of toxoplasma gondii. "KEGG analysis showed that KCTD12-related genes were mainly enriched in Kaposi sarcoma-associated herpes virus infection, the apelin signaling pathway, and toxoplasmosis." (PMID 37626178, 2023). "KEGG analysis further revealed enrichment in immune- and infection-related pathways (e.g., HTLV-1 infection, tuberculosis, toxoplasmosis), adhesion signaling (focal adhesion), and metabolic regulation (apelin signaling, amino acid biosynthesis)." (PMID 41050653, 2025). "The results of KEGG enrichment analysis revealed that the 32 intersecting genes were primarily enriched in the MAPK signaling pathway, B cell receptor signaling pathway, HIF-1 signaling pathway, toxoplasmosis, apelin signaling pathway, oxytocin signaling pathway, and cGMP-PKG signaling pathway." (PMID 37251077, 2023).
asthma (3 papers, 2013 to 2021). "We found that transcripts regulated in the lung tissues of these model mice could be mapped to signaling pathways, such as the Asthma pathway, Apelin signaling pathway, and cGMP-PKG signaling pathway." (PMID 30761008, 2018). "However, in our previous papers we confirmed high apelin concentration in children with asthma." (PMID 23476106, 2013). "The current study was designed to examine the circulating apelin, resistin, and visfatin levels in children with AD, who had no current additional allergic symptoms such as asthma and allergic rhinitis." (PMID 23476106, 2013).
Cachexia (3 papers, 2014 to 2025). Severe weight loss, wasting of muscle, loss of appetite, and general debility related to a chronic disease. "Apelin regulates skeletal muscle adaptation to exercise and Apelin resistance contributes to cachexia-induced muscle loss." (PMID 39948634, 2025). "We believe that the beneficial effects of apelin during cachexia are hampered by APJ unresponsiveness in muscles." (PMID 35406586, 2022). "Altogether, we believe that during cachexia apelin resistance occurs, contributing to muscle wasting and nullifying any possible peptide-based treatment." (PMID 35406586, 2022). "In agreement with others who report increased plasma levels of apelin in human cancers, especially gastro-esophageal ones, we also describe the increased apelin in the blood of multiple cancer-bearing mouse models with cachexia." (PMID 35406586, 2022). "Despite other cells present in muscles, muscle fibers were indeed less expressing apelin in vivo during cachexia." (PMID 35406586, 2022). "Puzzlingly, the levels of circulating apelin seemingly deriving from cachexia-inducing tumors, increase in murine plasma during cachexia." (PMID 35406586, 2022). "To shed light on the possible role of apelin in cachexia in vivo, we generated apelin 13 carrying all the last 13 amino acids of apelin in D isomers, ultimately extending plasma stability." (PMID 35406586, 2022). "Furthermore, we generated de-novo apelin 13-based peptides where all the amino acids appear as D isomers and evaluated them against cachexia in mice." (PMID 35406586, 2022). "Overall our data indicate that during C26 tumor induced-cachexia, apelin resistance may occur and worsen the progression of muscle wasting." (PMID 35406586, 2022). "Further work is needed to see whether dexamethasone reduces apelin via miRNA and if the same occurs in adult muscles with cachexia or in dexamethasone-treated adipocytes." (PMID 35406586, 2022). "Tumor apelin did not significantly correspond with cachexia status (P = 0.262) or any of pathological variables (P = 0.631 for the disease stage, P = 0.875 for T status, and P = 0.980 for N status)." (PMID 25049439, 2014). "Apelin downregulation and APJ desensitization in cachectic muscles may translate into reduced capillarization, possibly contributing to the oxidative-to-glycolytic metabolism switch seen in muscle with cachexia." (PMID 35406586, 2022). "Contrary to musclin, which may still be produced by cachectic muscle under exercise and exerts its anti-catabolic action, apelin that is equally increased during exercise could not counteract cachexia because of receptor desensitization." (PMID 35406586, 2022).